KLHL3 (kelch like family member 3)
Diseases named in the same sentence as KLHL3 in open-access papers (continued):
Sharing a sentence is not in itself a finding about the gene and the disease.
type 1 diabetes (2 papers, 2023 to 2026). "KLHL3 also plays different roles in type 1 diabetes (T1D) and type 2 diabetes (T2D), with hyperglycemia causing increased NEDD8 in diabetic mice, resulting in increased degradation of KLHL377." (PMID 37779139, 2023). "Allograft rejection, asthma, fatty acid biosynthesis, glycosphingolipid biosynthesis, graft‐versus‐host disease, nitrogen metabolism, primary immunodeficiency, protein export, starch and sucrose metabolism, and Type I diabetes mellitus were associated with KLHL3 function." (PMID 41542228, 2026).
COVID-19 (1 paper, 2025). A disease caused by infection with severe acute respiratory syndrome coronavirus 2. "Our analysis of the cis-eQTL effects of the SNP rs1042665 HSPA9 suggests a complex interplay of gene regulation involving KDM3B, ETF1, FAM53C, KLHL3, and DNAJC18, potentially contributing to COVID-19 severity." (PMID 41009536, 2025).
heart failure (1 paper, 2021). Inability of the heart to pump blood at an adequate rate to meet tissue metabolic requirements. "Three of the genes associated with heart failure had treatment cASE: FAM241A in five conditions (copper, dexamethasone, insulin, caffeine, and vitamin A); BAG3 in five conditions (dexamethasone, caffeine, vitamin A, nicotine, and aldosterone); and KLHL3 in triclosan." (PMID 33988505, 2021).
hepatoma (1 paper, 2022). "Additionally, KLHL3 or DN-KLHL3 overexpression in a hepatoma cell line did not affect the activity and half-life of AMPKα (data not shown)." (PMID 36028759, 2022).
pseudohypoaldosteronism (1 paper, 2023). An inherited or acquired disorder of electrolyte metabolism, characterized by the inability of the renal tubules to respond to aldosterone. "Nine patients were confirmed with aldosterone resistance, of which one child was diagnosed with pseudohypoaldosteronism (PHA) type 1 with a mutation in the NR3C2 gene and 3 children were identified with PHA type 2 due to novel mutations in either the CUL3 or KLHL3 genes." (PMID 36726778, 2023).
Sensory neuropathy (1 paper, 2024). Peripheral neuropathy affecting the sensory nerves. "However, a larger cohort size and further studies are needed to confirm this association between KLHL3 variants and sensory neuropathy." (PMID 39553548, 2024). "Exome sequencing revealed in all affected members two missenses at heterozygous state, one pathogenic variant in KLHL3, which may be responsible for the sensory neuropathy." (PMID 39553548, 2024). "This is the first description of sensory neuropathy associated with KLHL3 mutation." (PMID 39553548, 2024). "In future research, it may also be relevant to check if Klhl3 knockout mice (Klhl3-/-) display a sensory neuropathy phenotype, and deregulation of sodium-voltage gated channels in the dorsal, root ganglia." (PMID 39553548, 2024). "The mechanism leading to sensory neuropathy in KLHL3 mutation is not currently understood." (PMID 39553548, 2024). "Moreover, KLHL3 gene should be included in genetic explorations of inherited sensory neuropathies." (PMID 39553548, 2024). "We propose to screen KLHL3 gene in patients presenting with both PHAII and sensory neuropathy symptoms." (PMID 39553548, 2024). "This scarcity of neurological signs in some patients could explain why sensory neuropathy related to KLHL3 has not been described before." (PMID 39553548, 2024).
Sepsis (1 paper, 2026). Sepsis is defined as life-threatening organ dysfunction caused by a dysregulated host response to infection. "The strong association of genes like S100A9 and KLHL3 with neutrophils, pivotal players in sepsis, suggests potential avenues for therapeutic targeting." (PMID 41542228, 2026). "For example, we identified that KLHL3 was mainly engaged in fatty acid biosynthesis, glycosphingolipid biosynthesis, and nitrogen metabolism in sepsis samples." (PMID 41542228, 2026). "FOXO1, KLHL3, and PCBP1 were weakly expressed in the sepsis group whereas MTF1, TMEM59, PIK3CB, and S100A9 were highly expressed in the sepsis group." (PMID 41542228, 2026).
cancer (5 papers, 2016 to 2023). A tumor composed of atypical neoplastic, often pleomorphic cells that invade other tissues. "There are many indications that the KLHL3 gene is linked to cancer development." (PMID 38203636, 2023). "Nevertheless, the role of KLHL3 in the pathogenesis of cancers formed through viral interaction appears to be well-proven." (PMID 38203636, 2023). "Eight of these had decreased expression in cancer (KLHL3, KLHL4, KLHL13, KLHL14, KLHL29, KLHL30, KLHL32, and KLHL33) while four genes (ENC1, KLHL12, KLHL17, and KLHL35) had patterns of up-regulated gene expression." (PMID 30647843, 2018). "These actions may stem from the influence of vitamin D on the expression of genes associated with collagen production, such as SHMT1, UGT1A6, and ITIH2.The anti-cancer properties of vitamin D are also supported by changes in KLHL3 and TTPA gene expression." (PMID 38203636, 2023). "Furthermore, we found that genes including LINC02270, PRH1, and KLHL3 were affected by germline TE insertions in 16, 16, and 15 OS patients, respectively, although their cancer-associated functions have never been reported before." (PMID 35013466, 2022).
infection (1 paper, 2023). The state of being infected such as from the introduction of a foreign agent such as serum, vaccine, antigenic substance or organism. "Researchers have found that KLHL3 mediates the infection and replication of KSHV-induced tumorigenesis." (PMID 38203636, 2023).
KLHL3 also shares sentences with these, for which no sentence is quoted: metabolic acidosis (3 papers); Acidosis (1); aneurysm (1); asthma (1); Bartter syndrome (1); chronic lymphocytic leukemia (1); diffuse large B-cell lymphoma (1); dilated cardiomyopathy (1); electrolyte imbalance (1); hereditary disease (1); Hyperchloremia (1); hyperthyroidism (1); Insulin resistance (1); nemalin myopathy (1); nephrogenic diabetes insipidus (1); nonalcoholic fatty liver disease (1); primary immunodeficiency (1); renal tubular disorders (1); steatosis (1).